IDH1 (isocitrate dehydrogenase (NADP(+)) 1)
Diseases named in the same sentence as IDH1 in open-access papers (continued):
Sharing a sentence is not in itself a finding about the gene and the disease.
glioma (continued). "The core glioma biomarkers, IDH1/2 were found at a lower prevalence (8/112, 7%) and the rest 104 patients had IDH wild-type tumors, while no 1p/19q deletions were identified." (PMID 33747896, 2020). "Adult patients with glioma with BRAFAMP and IDH1/2WT had worse prognoses compared with those with BRAF mutation and BRAFAMP and IDH1/2MT." (PMID 33489866, 2020). "In general, MET uptakes in IDH1-wildtype gliomas were significantly higher compared with those in IDH1-mutant gliomas." (PMID 32382870, 2020). "Ivosidenib (AG-120) is a targeted mutant IDH1 inhibitor under evaluation in a phase 1 dose escalation and expansion study of IDH1-mutant advanced solid tumors including cholangiocarcinoma, chondrosarcoma, and glioma." (PMID 31028664, 2020). "We calculated a second, separate immunocytochemical measure of tumor infiltration by quantifying high-grade glioma cells that were positive for either nestin or for IDH1 (R132H) mutant protein at the core and tumor edge." (PMID 32226940, 2020). "In the present study, more than 50% of the gliomas were GBMs, and almost all GBMs were IDH1-wildtype (43/45 cases)." (PMID 32382870, 2020). "Mutations in IDH1 and IDH2 genes are present in a majority of the low-grade gliomas and define a subtype associated with favorable prognosis." (PMID 33272320, 2020). "Gliomas with low CASC2 expression exhibited a high level of miR-21, which was highly associated with the higher glioma grade (p = 0.0001), IDH1 wild type gliomas (p < 0.0001), and poor patient survival (p < 0.001)." (PMID 33120918, 2020). "Focusing on post-TMZ recurrent gliomas that have MGMT promoter methylation and/or IDH1 mutations increases the per-case value of such screening." (PMID 32051040, 2020). "Regarding the immunohistochemical study, only one recurrent gcGBM from a low-grade glioma (case #35) was positive for IDH1 p.R132H immunohistochemistry." (PMID 32642724, 2020). "Isocitrate dehydrogenase 1 (IDH1) mutation, which occurs early in gliomagenesis, especially for WHO grade II and III gliomas, is an acknowledged molecular alteration." (PMID 33229627, 2020). "There are many experiments to discover new therapeutic medications such as small molecules or drugs to target IDH1/2 in low-grade gliomas conducted and some have progressed to validation in humans." (PMID 33221817, 2020). "Through a Rictor/mTOR2/RAC1/WAVE2 axis, these IDH1-mutant glioma cells overcome metabolite depletion by endocytosing beneficial ECM material, promoting tumor resistance." (PMID 32545340, 2020). "Histogram parameters of Ktrans, Ve and VEGF expression of IDH1 mutant type (IDH1mut) gliomas were compared with the IDH1 wildtype (IDH1wt) gliomas." (PMID 33425744, 2020). "Typically, tumor suppressor genes exhibit an increased expression in gliomas with mutant IDH1, whereas the expression of oncogenes declines." (PMID 31847543, 2020). "IDH1 mutation was a key genetic event that mainly occurs in lower grade gliomas, while the IDH1 wild-type phenotype constituted the GBM group." (PMID 33229627, 2020). "For example, the amino acid glycine is elevated in poor prognosis cases of IDH1-mutant glioma patients." (PMID 32587392, 2020). "Recently, it was discovered that cyclin F is upregulated under metabolic stress conditions and inhibits tumorigenesis mediated by an oncogenic mutant form of isocitrate dehydrogenase 1 (IDH1), IDH1-R132H, in glioma." (PMID 31884567, 2020). "Lastly, by giving our perspective on the benefits and limitations of patient-derived and donor-derived disease modeling respectively, we aim to propose leading research questions to be answered in the context of IDH1 and glioma." (PMID 33221817, 2020). "The results of univariate regression showed that HLA-F (p < 0.001) along with grade (p < 0.0001), age (p < 0.0001), and IDH1 status (p < 0.0001) predicted the OS in all grade gliomas." (PMID 30755240, 2019).
glioma (continued). "IDH1 or IDH2 mutations can exist in glioblastomas, especially evolved from lower-grade gliomas, and patients with such tumors had a better outcome than those with wild-type IDH genes." (PMID 31138312, 2019). "Recently, in IDH1-mutant gliomas, the therapeutic effect of AZA is further enhanced in combination with TMZ." (PMID 31652645, 2019). "In an early preclinical study of IDH1-mutant gliomas, AGI-5198, the first selective mutant IDH1 inhibitor, showed tumor growth inhibition along with astroglial differentiation." (PMID 31652645, 2019). "We extend the study to three grade III glioma cell lines: BT142 mut/−, harboring a homozygous R132H mutation, and SW1088 and MOG-G-CCM, wild type for IDH1." (PMID 31428936, 2019). "IMMs effectively blocked invasion in patient-derived neuro-spheres in multiple IDH1-wild-type high-grade glioma patient samples." (PMID 30897774, 2019). "Some tumors are characterized by the prevalence of a mutation in a specific gene, such as the G-protein coding BRAF in thyroid carcinoma or IDH1, translating into isocitrate dehydrogenase, in low-grade glioma." (PMID 31379928, 2019). "Mutations in the IDH1 and 2 genes initially occur in WHO grade II and grade III gliomas and are associated with improved survival." (PMID 31296788, 2019). "IDH1 induction, leading to lipid biosynthesis and decreased ROS production, has been explained as an adaptive response of glioma cells to growth factor receptor inhibition." (PMID 31010244, 2019). "The cytoplasmatic isoform IDH1 is found in the nuclei of glioma cells, likely involved in histone and DNA methylation." (PMID 31366176, 2019). "Here we present a case of a young man with a high grade IDH1-mutant glioma with abnormalities in chromosomes 1 and 19 who experienced an unusually aggressive disease progression following standard therapy for anaplastic oligodendrogliomas." (PMID 30738431, 2019). "Most recently, a phase 1 trial in gliomas has been launched to determine the safety and tolerability of IDH1 R132H peptide vaccine, PD-L1 checkpoint inhibitor (Avelumab) or their combination (ClinicalTrials.gov NCT03893903)." (PMID 31652645, 2019). "For example, IDH1, a strong driver in glioma, shifts gene expression towards the cell division archetype." (PMID 31780652, 2019). "Consistent with previous studies, patients with mutant IDH1 had a significantly reduced hazard of death relative to wild-type IDH1 glioma patients." (PMID 31091655, 2019). "Mutation of the gene encoding isocitrate dehydrogenase (NADP(+)) 1, (IDH1) at arginine 132 or IDH2 at arginine 172 is associated with secondary GBM, GBM that has arisen from lower grade glioma." (PMID 30894629, 2019). "Consistently, antitumor immunity to experimental syngeneic IDH1-mut gliomas induced by an IDH1-specific vaccine or checkpoint inhibition was significantly improved by inhibition of the enzymatic function of mutant IDH1." (PMID 30857299, 2019). "IDH1 and IDH2 are mutated in over 75% of low grade gliomas and secondary glioblastoma multiforme (GBM)." (PMID 31311166, 2019). "IDH1 was the most frequently mutated gene in LGG (77.3% in our data) and known to regulate cell cycle of glioma cells and enhance the response to chemotherapy." (PMID 30704458, 2019). "Since the initial discovery of IDH mutations in cancer in 2008, recurrent somatic mutations in IDH1 and IDH2 have been identified in different malignancies, including gliomas, thyroid carcinomas, cholangiocarcinomas, sarcomas, and AML." (PMID 31695915, 2019).
glioma (continued). "Among these molecular markers, IDH1, 1p19q, and MGMT methylation are closely associated with the prognosis and chemotherapy sensitivity of glioma patients." (PMID 30995921, 2019). "It is suggested that receptor tyrosine kinases (RTKs) inhibitors increase IDH1 production in glioma cells via an RTK-PI3K-Akt-FoxO6 signaling axis." (PMID 31010244, 2019). "AG-881(Vorasidenib), a pan-inhibitor of both mutant IDH1 and mutant IDH2, exhibits effective brain penetration accompanied by suppression of 2-HG production in an orthotopic glioma model (IDH1 R132H)." (PMID 31652645, 2019). "The lack of nestin/GFAP expression changes in human primary glioblastoma cells implicates no induction of cell differentiation by the treatments, although such responses have been described for 5-aza-dC in hypermethylated IDH1-mutant secondary gliomas." (PMID 31639020, 2019). "In 2016, it has been reported that AG-120 displays a 35% clinical benefit rate and a favorable safety profile in phase 1 trial in IDH1-mutant gliomas (ClinicalTrials.gov NCT02073994)." (PMID 31652645, 2019). "A population-based study that analyzed 3 molecular markers (1p/19q, IDH1/2, and TERT promoter) stratified grade II and III gliomas into five molecular subgroups independently associated with clinical outcomes." (PMID 31788444, 2019). "Results from GSE16011 showed that: glioma, LGG and LGG with IDH1 mutation patients with high EN1 expressions had significantly shorter 5, 10, and 15-year overall survival time (OS) (p < 0.001)." (PMID 31576231, 2019). "Among the more robustly discriminating hallmarks between IDH1 wildtype from IDH1mutant gliomas is that of angiogenesis." (PMID 31881020, 2019). "Current practice is to utilize Clinical Laboratory Improvements Amendments (CLIA)-approved and commercially available monoclonal antibodies (mAbs) for the most common mutation of IDH1 and ATRX for routine grading of gliomas." (PMID 31091655, 2019). "At least one of a set of 36 genes involved in chromatin and histone modifications is frequently altered in gliomas, most of which belonged to the IDH1/2 mutant-non-1p/19q-codeleted group." (PMID 30644073, 2019). "Point mutations in IDH1 and IDH2 are detected in different types of malignancies such as glioma and glioblastoma, acute myeloid leukemia (AML), and head and neck squamous cell carcinoma (HNSCC)." (PMID 30744183, 2019). "The discovery of mutations in isocitrate dehydrogenase 1 (IDH1) and 2 (IDH2) in over 80% of low-grade gliomas (LGGs) and secondary glioblastomas has revolutionized pharmaceutical approaches to targeted therapies and the overall glioma classification schema." (PMID 31165048, 2019). "Currently, IDH1 and IDH2 mutations have been identified in acute myelogenous leukemia, low-grade glioma, and secondary glioblastoma." (PMID 31263678, 2019). "IDH1/2 mutations are observed in >70% of grade II and grade III gliomas and more than 90% of secondary glioblastomas." (PMID 31652923, 2019). "Since IDH1/2 mutants enzyme inhibitors have good application prospects in pre-clinical research and clinical trials of glioma, we believe that IDH1/IDH2 mutant enzyme inhibitors will bring new hope to glioma patients." (PMID 31263678, 2019). "To gain new clinical- and biological-insights into the genetically-bifurcated IDH1 mutant (mt) vs wildtype (wt) forms of glioma, we integrated data from protein, genomic and MR imaging from 20 treatment-naïve glioma cases and 16 recurrent GBM cases." (PMID 31881020, 2019). "Currently, a phase 1 study of IDH1-mutant gliomas is ongoing for determining the maximum tolerated dose (MTD) of ASTX727, which consists of DAC and E7727 (cedazuridine), a novel CDA inhibitor (ClinicalTrials.gov NCT03922555)." (PMID 31652645, 2019). "Specifically, IDH1 mutant gliomas exhibit hypermethylation at cohesin and CTCF-binding sites, thereby inhibiting the CTCF binding that is crucial for proper organization of TADs." (PMID 30644073, 2019).
glioma (continued). "Subsequent work has demonstrated that IDH1-mutant gliomas correlated with lower expression of the T cell attracting chemokines CXCL9 and CXCL10, and subsequent reduction in number of CD3+, CD8+ tumor infiltrating lymphocytes." (PMID 31781488, 2019). "As is known to all, IDH1/2 mutation and MGMT promoter methylation are two important biomarkers in glioma." (PMID 31379707, 2019). "In particular, combining AZA and TMZ significantly reduces tumor growth and extends the survival of mice in subcutaneous and intracranial xenografts of IDH1-mutant gliomas, respectively." (PMID 31652645, 2019). "In this study, we investigated the relationship between SWI features and glioma grades, and the expression of key molecular markers isocitrate dehydrogenase 1 (IDH1), O-6-methylguanine-DNA methyltransferase (MGMT), and 1p19q." (PMID 31745161, 2019). "The incidence of IDH1 (R132H) expression that we detected in all intermediate-grade glial tumors included in the study is consistent with the high values reported in the literature." (PMID 30592195, 2019). "Phase I studies of another two mutant IDH1 inhibitors (AGI-881, NCT02481154; AG-120) showed a favorable safety profile and potential efficacy in patients with IDH mutated gliomas." (PMID 31450721, 2019). "AG-120 is currently being evaluated in several clinical trials for the therapy of patients with relapsed or refractory AML, myelodysplastic syndrome, and advanced solid tumors including glioma, chondrosarcoma, and cholangiocarcinoma with a mutant IDH1/R132H." (PMID 30857299, 2019). "The search within the Treehouse public expression dataset reveals a higher occurrence of IDH1 within the diffuse intrinsic pontine glioma (compared to glioma, glioblastoma multiforme and gliomatosis cerebri)." (PMID 30675185, 2019). "Low-grade gliomas and secondary glioblastomas are characterized by mutations in IDH1/2 (isocitrate dehydrogenase 1/2), which are associated with a longer overall survival and better response to therapy compared to IDH-wildtype gliomas." (PMID 31888244, 2019). "Both mutated IDH1 and IDH2 are common in adult gliomas (WHO grades II and III) and secondary GBM (WHO grade IV)." (PMID 30625996, 2019). "The results emphasize the important role of mutant IDH1 in treatment of patients with gliomas especially in response to radiation." (PMID 31242696, 2019). "Mutations in IDH genes (IDH1 and IDH2) have been revealed in the majority of lower-grade gliomas and in secondary glioblastoma multiforme, and predict better survival." (PMID 31444316, 2019). "With respect to the field “epigenetics,” the discovery of mutation to the IDH1 and IDH2 genes in gliomas has determined the prosperity of subsequent glioma and epigenetic studies." (PMID 30717468, 2019). "Among the three IDH enzymes, IDH1 and IDH2 are frequently mutated in glioma and hematological malignancies." (PMID 31695915, 2019). "A phase 1 trial is currently ongoing in IDH1-mutant advanced solid tumors, including gliomas (ClinicalTrials.gov NCT02746081)." (PMID 31652645, 2019). "IDHmut glioma is distinct in being the only cancer in the entire body to show enrichment for R132H IDH1." (PMID 31222125, 2019). "In contrast, primary GBM (IDH1 wild-type) showed increased mTORC1 pathway expression and activation when compared to wild-type low-grade gliomas." (PMID 31052505, 2019). "Among the numerous molecular characteristics of glioma, IDH gene mutations are the most critical, of which IDH1 mutation is closely associated with a good prognosis and favorable survival in patients." (PMID 31745161, 2019). "Further studies have found that IDH1, or IDH2 mutation, happens in ~80% of WHO grade II–III gliomas and secondary GBM." (PMID 31450721, 2019).
glioma (continued). "Recently, increasing evidence has suggested recurrent point mutations in isocitrate dehydrogenase genes (IDH1 and IDH2) occur in specific types of glioma." (PMID 31681612, 2019). "Mutations in IDH1 and IDH2 are seen in over 80% of lower-grade gliomas (WHO grades II and III) and secondary GBMs that are thought to later develop from lower-grade lesions." (PMID 31165048, 2019). "Consider for example, the 2-hit combination of mutations in IDH1 and MUC6 in brain lower grade glioma (LGG) tumor samples." (PMID 30700767, 2019). "The newly formed tumor microenvironment provides nutritional support for glioma cells through exosomes, and a large amount of IDH1 mRNA expression is detected in the cerebrospinal fluid of glioma patients." (PMID 31263678, 2019). "Ten years ago, our understanding of the molecular landscape in glioma was transformed by the first genome-wide analysis of somatic mutations in glioblastoma (GBM) and the identification of recurrent mutations in IDH1 nearly exclusively in secondary GBM." (PMID 31165048, 2019). "Both pSmad1-positive and pSmad2-positive cell populations were IDH1-mutant, confirming their identity as glioma cells." (PMID 31602000, 2019). "To validate our findings in vivo we analyzed the tissue of two previously generated intracranial patient-derived xenografts (PDX) of glioma, one IDH1-wildtype glioblastoma and one oligodendroglioma with the IDH1R132H." (PMID 31888244, 2019). "It has been reported that mutations of IDH1 and IDH2 occur in the vast majority of low-grade gliomas and secondary high-grade gliomas, and also in some cases of AML." (PMID 30984620, 2019). "The most frequent mutation in the IDH1/2 genes is the IDH1-R132H, which is described in the majority of grade II and grade III gliomas." (PMID 31357616, 2019). "IDH1 expression has been regarded as an independent prognostic factor for glioma patients’ survival rate." (PMID 31450822, 2019). "Gene expression profiles from these gliomas co-clustered with those of the p.IDH1-R132H gliomas in cluster B (black in IDH-status annotation bar)." (PMID 31747973, 2019). "In our results, the expression levels of PSAT1 were also significantly higher in grade II and III gliomas with IDH1 mutations than in those of IDH1 wild-type, and significantly higher in grade II gliomas than in grade III gliomas." (PMID 31861486, 2019). "In this study, we have evaluated several orthotopic mouse glioma models, including transgenic mice (IDH1 R132H knocking), virus or chemical‐induced GBM model." (PMID 30834619, 2019). "IDH2 mutations, which are mutually exclusive with those in IDH1 and found at a functionally analogous R172 residue, only represent a minority of somatic IDH mutations in glioma." (PMID 31165048, 2019). "Instead, gain-of-function mutations of IDH1 and IDH2 isoforms lead to the production and accumulation of L- and D-2-hydroxyglutarate (L-/D-2HG) in acute myeloid leukemia, glioma, chondrosarcoma, and cholangiocarcinoma." (PMID 31366176, 2019). "Similar efforts to characterize GBM have revealed that, whilst several molecular subtypes exist, only the glioma-CpG island methylated phenotype (G-CIMP), which harbor the IDH1-R132H mutation, is predictive of longer patient survival." (PMID 31405148, 2019). "We found that the expression of NAMPT is lower in patient-derived IDH1-mutant glioma cells and xenografts compared to IDH1-wildtype models." (PMID 31888244, 2019). "In 2008–2009, a pair of studies reported a surprisingly high proportion of infiltrative gliomas with IDHmut, most commonly R132H IDH1; such tumors tended to be much less aggressive than their IDHwt counterparts." (PMID 31222125, 2019). "The Cancer Genome Atlas (TCGA) data analysis confirmed lower NAMPT expression in IDH1-mutant versus IDH1-wildtype gliomas." (PMID 31888244, 2019).